Y_RNA (Y RNA )
Gene: Miscellaneous RNA gene on chromosome 12 (60,341,824 to 60,341,941, reverse strand). Ensembl gene ENSG00000252607.
Homologues: Orthologues: macaque Y_RNA (81% identical). Paralogues in human: RNY1 (81% identical), RNY1P11 (81% identical), Y_RNA (81% identical), RNY1P10 (80% identical), Y_RNA (80% identical), Y_RNA (79% identical), RNY1P8 (78% identical), Y_RNA (78% identical), Y_RNA (77% identical), Y_RNA (76% identical), Y_RNA (75% identical), RNY1P12 (75% identical), and 92 more.